TRIB3 (tribbles pseudokinase 3)
Diseases named in the same sentence as TRIB3 in open-access papers (continued):
Sharing a sentence is not in itself a finding about the gene and the disease.
bladder cancer (continued). "Expression of TRIB3 positively correlated with stage and grade and down-regulation of TRIB3 expression significantly inhibited proliferation, migration and cell cycle of bladder cancer cells." (PMID 33841505, 2021). "Another important finding was that TRIB3 is a potential oncogene in bladder cancer." (PMID 33841505, 2021). "Overall, TRIB3 successfully predicted outcomes in patients with bladder cancer in four cohorts." (PMID 33841505, 2021). "TRIB3 expression promotes the proliferation and invasion of bladder cancer cells." (PMID 33841505, 2021). "Flow cytometry analysis revealed that arrested G0/G1 cell cycle could be induced by TRIB3-siRNA, confirmed by statistical analysis, thereby inhibiting the proliferation and migration of bladder cancer cells." (PMID 33841505, 2021). "Finally, we used Sanjeev’s bladder cancer cohort for verification, and it was found that TRIB3 still had the ability of prognosis (p < 0.05)." (PMID 33841505, 2021). "Our study identified FOXD2-AS1 was engaged in a novel modulatory mechanism of TRIB3 and PI3K/Akt pathway, which might serve as an essential cause of bladder cancer relapse." (PMID 29445134, 2018). "However, few studies reported the role of TRIB3 expression in bladder cancer." (PMID 33841505, 2021). "Tribbles pseudokinase 3 (TRIB3) is a pseudokinase that participates in cell tumor progression and metabolism and whose function in bladder cancer is not precisely known." (PMID 33841505, 2021).
cardiomyopathy (4 papers, 2017 to 2023). A disease of the heart muscle or myocardium proper. "Trib3 knockdown in rat and mouse diabetic models reduces the destructive effects of diet on cardiomyopathy, making Trib3 a candidate target to alleviate metabolic disease." (PMID 29025897, 2017). "Genes associated with ER stress (e.g., ATF4, NUPR1, DDIT3, TRIB3, CHAC1, SESN2, HERPUD1) were upregulated and genes related to cardiomyopathy and sarcomeric structure (e.g., MYH7, SYNPO2L, LDB3, ACTN2, MYLK3) were downregulated by afatinib, sorafenib, or high-dose ponatinib." (PMID 37069550, 2023). "TRIB3 is a known regulator of MAPK–ERK pathway in cancer and cardiomyopathy models by directly interacted with ERK or increased posttranslational phosphorylation." (PMID 33192545, 2020).
diabetic nephropathy (4 papers, 2017 to 2025). "Previous studies have implicated TRIB3 signaling in diabetic nephropathy and atherosclerotic vascular diseases." (PMID 39932798, 2025). "The TRIB3 ‘G’ allele was identified as associated with diabetic nephropathy and it was suggested that this observation may help to improve targeting of therapy to diabetic patients." (PMID 28761062, 2017).
head and neck squamous cell carcinoma (4 papers, 2023 to 2025). A squamous cell carcinoma that arises from any of the following anatomic sites: lip and oral cavity, nasal cavity, paranasal sinuses, pharynx, larynx, and salivary glands. "Chen and colleagues reported that tribble protein kinase 3 (TRIB3) promoted head and neck squamous cell carcinoma (HNSCC) progression by weakening ferroptosis." (PMID 40552277, 2025). "By preventing ferroptosis, a novel oncogene called tribbles pseudokinase 3 (TRIB3) increases the aggressiveness of head and neck squamous cell carcinoma." (PMID 38674143, 2024). "While its significant role in the immune regulation of certain cancers is well-established, the specific functions and impact of TRIB3 in head and neck squamous cell carcinoma (HNSC) remain unclear." (PMID 38235126, 2023).
lung adenocarcinoma (4 papers, 2020 to 2025). A carcinoma that arises from the lung and is characterized by the presence of malignant glandular epithelial cells. "In lung adenocarcinoma cells, TRIB3 knockdown decreased levels of HIF-1α, indicating a feedback loop between TRIB3 and HIF-1α, where one can regulate the other." (PMID 38896446, 2024). "Currently, the m6A modification of TRIB3 mRNA was found in lung adenocarcinoma, but TRIB3 mRNA-associated m6A modification has not been reported in HCC." (PMID 39910904, 2025).
colorectal tumors (3 papers, 2016 to 2024). "has shown that inhibition of TRIB3 signalling increases CD8+ T cell accumulation in colorectal tumours in a similar STAT3/STAT1/CXCL10 dependent mechanism." (PMID 39165364, 2024). "These eight isoforms encoded by OGDH, COL6A3, ICAM1, PHPT1, PPP2R5D, SLC29A1, and TRIB3 genes were up-regulated in colorectal tumors, and this is in concordance with the bioinformatics data." (PMID 28105922, 2016).
coronary heart disease (3 papers, 2022 to 2026). "Human relevance was assessed by testing efferocytosis in macrophages from individuals carrying the TRIB3 Q84R coronary artery disease risk variant (rs2295490) and by examining carotid endarterectomy samples." (PMID 41186004, 2025). "CA9, CBS, CEBPG, HSPB1, SLC1A4, HSPB1 and TRIB3 are genes that we have screened for iron death in coronary heart disease samples." (PMID 35152560, 2022).
kidney cancer (3 papers, 2016 to 2023). Primary or metastatic malignant neoplasm involving the kidney. "We found that the uc002wdm/NM_021158 (TRIB3) mRNA level was increased in 73.3% (22 of 30, p < 0.05), 50% (15 of 30, p < 0.05), and 93.3% (28 of 30, p < 0.05) cases of breast, prostate, and kidney cancers, respectively." (PMID 28105922, 2016). "To validate the differential expression of TRIB3, we used HK-2 (an immortalized proximal tubule epithelial cell line from a normal adult human kidney) and A498 (a cell line with epithelial morphology that was isolated from a kidney cancer patient) cells for exploration." (PMID 38006403, 2023).
lung fibrosis (3 papers, 2022). "Based on the reanalysis of a published dataset (GSE129164), we found that stimulation of lung fibroblasts of IPF patients and normal controls with TGF-β1 (the principal profibrotic cytokines in lung fibrosis) increased TRIB3 mRNA expression." (PMID 35668944, 2022). "TRIB3 attenuated pulmonary fibrosis by negative regulation of ATF4, while TRIB3 expression markedly inhibited ATF4 promoter-driven transcription activity and down-regulated ATF4 expression." (PMID 36555349, 2022). "In the present study, we demonstrated that TRIB3 contributes to the A549 epithelial cells’ proliferation and migration and repair; TRIB3 attenuates pulmonary fibrosis by interacting with ATF4." (PMID 36555349, 2022). "Elevated TRIB3 expression was observed in alveolar macrophages (AMs) from bleomycin challenged fibrotic mice, which contributes to pulmonary fibrosis (PF)." (PMID 36555349, 2022). "To investigate the molecular mechanisms of TRIB3 attenuating lung fibrosis, we postulated that TRIB3 plays a momentous role in IPF through regulation of ATF4." (PMID 36555349, 2022). "Tribble’s homolog 3/glycogen synthase kinase-3β (TRIB3‒GSK-3β) interactions promote lung fibrosis and could be used as the potential therapeutic target." (PMID 36479199, 2022). "Taken together, our findings showed that increased TRIB3 expression may assist in reducing lung fibrosis in vitro." (PMID 36555349, 2022). "TRIB3 expression negatively regulated ATF4 expression, which promoted fibroblast proliferation, migration, and activation contributing to pulmonary fibrosis." (PMID 36555349, 2022).
retinal degeneration (3 papers, 2021 to 2024). Degeneration of the retina. "The application of both strategies reduced TRIB3 activity and significantly mitigated retinal degeneration in these mice." (PMID 38731938, 2024). "Because of our recent findings suggesting the regulation of p-AKT/p-mTOR by the pseudokinase TRIB3 in mice with inherited retinal degeneration and the TRIB3 upregulation in human and mouse diabetic retinas, we tested the TRIB3 levels as well." (PMID 35046899, 2021). "Based on the results, we then proposed that modulation of TRIB3 levels may retard retinal degeneration and that TRIB3 may be a promising therapeutic target to treat various retinal degenerative disorders." (PMID 38731938, 2024). "The previous study with rd16 mice showed that TRIB3 ablation delays retinal degeneration." (PMID 38731938, 2024). "Using two mouse models of RD with different etiologies and rates of retinal degeneration, along with two therapeutic approaches (targeting TRIB3 levels via pharmacological intervention and TRIB3 pseudokinase activity via CPP delivery to the retina), we delayed the onset of retinal degeneration." (PMID 38731938, 2024). "In the current study, we provided evidence that pharmacologically targeting TRIB3 results in reduced TRIB3 protein levels in P23H RHO retinas and delays retinal degeneration in rd10 mice." (PMID 38731938, 2024). "However, the TRIB3-mediated control of p-AKT in the retina of mice with inherited retinal degeneration did not coincide with the present results on the diabetic retina, implying that the cellular signaling may be differentially activated depending on the type of stress." (PMID 35046899, 2021).
rhabdomyosarcoma (3 papers, 2024 to 2025). A rare aggressive malignant mesenchymal neoplasm arising from skeletal muscle. "Emerging evidence also points to TRIB3 as a contributor to chemoresistance in rhabdomyosarcoma, suggesting a broader role in therapeutic evasion and disease recurrence." (PMID 40508013, 2025). "TRIB3 is not specific to alveolar rhabdomyosarcoma (ARMS); rather, it is a stress-response gene expressed across multiple sarcoma subtypes." (PMID 40508013, 2025).
systemic sclerosis (3 papers, 2017 to 2024). A chronic disorder, possibly autoimmune, marked by excessive production of collagen which results in hardening and thickening of body tissues. "Consistent with our observations in OC metastasis, TGF-β1 has also been reported to upregulate TRIB3 expression in an SMAD3-dependent manner in fibroblasts in systemic sclerosis and murine alveolar type II epithelial cells." (PMID 39719444, 2024). "Another study found a central regulatory role of TRIB3 in fibroblast activation by stimulating canonical TGF-β1/Smad signaling in systemic sclerosis." (PMID 35668944, 2022). "TRIB3 plays an important role in fibroblast activation in systemic sclerosis (SSc) by activating the canonical TGF-β/SMAD signaling pathway and stimulating the release of collagen, thereby inducing a positive feedback loop that may contribute to aberrant TGF-β signaling in SSc24." (PMID 28871113, 2017).
triple-negative breast carcinoma (3 papers, 2019 to 2021). An invasive breast carcinoma which is negative for expression of estrogen receptor (ER), progesterone receptor (PR), and human epidermal growth factor receptor 2 (HER2). "Noteworthy previous studies had shown that TRIB3 promotes tumor development and resistance to therapy in triple negative breast cancer models by regulating the NOTCH pathway or the stability of SOX2 via AKT inhibition and stabilization of FOXO1." (PMID 34771470, 2021). "Studies that were performed in triple negative breast cancer models indicated that TRIB3 can promote tumor development and resistance to therapy." (PMID 34771470, 2021). "Our previous study revealed that TRIB3 can interact with DDX5/BNIP/BCLAF1 in radioresistant MDA-MB-231 cells; thus, it is involved in the self-renewal and radioresistance of triple-negative breast cancer cells by regulating Notch1 activation." (PMID 33334065, 2020).
virus infection (3 papers, 2017 to 2024). "The involvement of TRIB3 in viral infection is poorly understood; however, its inhibition was associated with an increase of hepatitis C virus (HCV) replication." (PMID 33532126, 2021). "Given that TRIB3 was previously reported to decrease virus infection and replication, the decreased expression of TRIB3 in aged lungs may help explain why older male patients are related to more severe cases of the COVID-19." (PMID 33532126, 2021). "Considering that TRIB3 may decrease virus infection and replication, strategies to stimulate TRIB3 expression should be tested to treat COVID-19." (PMID 33532126, 2021). "Although TRIB3 has been reported to negatively regulate FGF21 promoter activity under nutrient deprivation conditions, its relevance to viral infection is unknown." (PMID 39211324, 2024).
cardiac hypertrophy (2 papers, 2020 to 2021). "Additionally, TRIB3 deficiency ameliorates metabolic disturbance inflammation, fibrosis, and myocardial hypertrophy in rats with dilated cardiomyopathy indicating the potential benefits of TRIB3 regarding its anti-fibrotic and metabolic modulating effects." (PMID 33192545, 2020).
cervical carcinoma (2 papers, 2014 to 2021). A carcinoma arising from either the exocervical squamous epithelium or the endocervical glandular epithelium. "For instance, the increase of TRIB3 expression in HeLa cervical carcinoma cells resulted in the inhibition of MAPK14, MAPK3/1 and MAPK8 (JNK) activities via binding to MAPK kinase." (PMID 24834131, 2014).
complication (2 papers, 2018 to 2022). Any disease or disorder that occurs during the course of, or because of, another disease, treatment, or procedure. "Our previous study revealed that TRIB3 genetic variations were strongly associated with diabetic vascular complications, although TRIB3 regulation pathways remain poorly understood." (PMID 30618737, 2018). "TRIB3 rs2295490, ATF6 rs12086247, and SMARCD3 rs58125572 genetic variants are associated with specific treatment protocols and with the incidence of diabetic vascular complications." (PMID 30618737, 2018).
high blood pressure (2 papers, 2014 to 2019). "Homocysteine, which is significantly associated with hypertension could up-regulate the expression of TRIB3, thus leading to the endothelial dysfunction." (PMID 30971918, 2019). "In conclusion, our data supported that TRIB3 (251, A > G) genetic polymorphism may serve as a useful biomarker in the treatment of hypertension." (PMID 30971918, 2019). "Baseline characteristics of patients with essential hypertension stratified by TRIB3 genotype." (PMID 30971918, 2019). "The purpose of the present study was to evaluate the association between four insulin resistance genes (ADIPOQ, LEPR, RETN, and TRIB3) and both T2DM and hypertension." (PMID 24414038, 2014). "However, the effect of TRIB3 genetic variation on antihypertensives was not clear in essential hypertension patients." (PMID 30971918, 2019).
Hyperinsulinemia (2 papers, 2017 to 2018). An increased concentration of insulin in the blood. "In vertebrates, hepatic Trib3 misexpression in mice leads to hyperinsulinemia, owing to its ability to block Akt-mediated glucose uptake." (PMID 29025897, 2017).
liver disease (2 papers, 2024 to 2025). "Our results suggest that MIST1 plays a key role in the regulation of apoptosis and TRIB3 expression contributing to progressive liver disease after injury." (PMID 39516480, 2024). "This study showed that MIST1 is a novel regulator of TRIB3 and suggested the potential of MIST1 as a marker of liver disease progression." (PMID 39516480, 2024).
lymph node metastasis (2 papers, 2020 to 2021). "In the tongue SCC, both TRIB3 and AKT were highly expressed compared to adjacent non-cancerous tissues, correlating TRIB3 overexpression with tumor pathological T stage, lymph node metastasis, and tumor recurrence." (PMID 34580365, 2021).
multiple myeloma (2 papers, 2021 to 2026). "Moreover, Pseudokinase TRIB3 promotes multiple myeloma progression by stabilizing SSRP1 through USP10-mediated deubiquitination, thereby enhancing oncogenic signaling and tumor growth." (PMID 41522354, 2026).
nasopharyngeal carcinoma (2 papers, 2023 to 2025). A carcinoma arising from the nasopharyngeal epithelium. "In malignant tumors of the head and neck (such as oropharyngeal cancer and nasopharyngeal carcinoma), TRIB3 can function to regulate cell functions via PI3K / AKT / mTOR signaling pathway." (PMID 39869954, 2025). "In the NPC_GSE150430 dataset, 45,959 cells from 15 patients with nasopharyngeal carcinoma were analyzed; TRIB3 shows elevated expression levels in malignant cells as well as in monocytes/macrophages and T cells." (PMID 38235126, 2023).
neuroblastoma (2 papers, 2016 to 2020). Neuroblastoma (NB) is the most common solid, extracranial childhood tumor. "Although treatment of neuroblastoma cells with ABTL0812 resulted in increased TRIB3 levels and bi-lipidation of LC3, the levels of AKT phosphorylation or its downstream targets PRAS40 and S6 were not modified at the time and doses analysed." (PMID 32943619, 2020).
oral squamous cell carcinoma (2 papers, 2021). "However, TRIB3 promoted oral squamous cell carcinoma cell proliferation by increasing Akt phosphorylation." (PMID 34503515, 2021).
osteosarcoma (2 papers, 2021 to 2023). A usually aggressive malignant bone-forming mesenchymal neoplasm, predominantly affecting adolescents and young adults. "Our research systematically discovered and verified four immune-associated candidate hub genes (ASNS, SRGN, CD70, TRIB3) with high predictive value for diagnosing osteosarcoma by bioinformatics analysis and machine learning algorithms." (PMID 37732314, 2023). "As a result, a total of five pivotal candidate genes (ASNS, SRGN, CD70, and TRIB3) were identified for diagnosing patients with osteosarcoma." (PMID 37732314, 2023). "After machine learning by SVM-RFE and LASSO regression model, four biomarkers were chosen for the diagnostic nomogram for osteosarcoma, including ASNS, CD70, SRGN, and TRIB3." (PMID 37732314, 2023). "Our results found that osteosarcoma patients with high TRIB3 (p = 0.017) and SRGN (p = 0.010) expression levels had longer overall survival times than those with low expression." (PMID 37732314, 2023). "According to our results, ASNS, CD70, and TRIB3 were upregulated in osteosarcoma patients, while SRGN was downregulated in osteosarcoma patients." (PMID 37732314, 2023). "Finally, a recent analysis of global transcriptome (RNA-Seq) showed that CRISPR/Cas9 knockout ERK5 human osteosarcoma U2OS cells express elevated levels of CHOP, TRIB3 an XBP-1 mRNAs, compared to wild type U2OS cells." (PMID 34805151, 2021). "In addition, TRIB3 was a negative modulator of CD8+ T cells in osteosarcoma." (PMID 37732314, 2023).
pancreatic cancer (2 papers, 2022 to 2024). "In our study, we found that gossypol treatment markedly upregulated the expression of PPP1R15A, Tribbles-related protein 3 (TRIB3), and ATF3 in pancreatic cancer cells." (PMID 35283426, 2022). "Therefore, although gossypol promotes apoptosis in various cancer cells, ER stress signaling is induced specifically in pancreatic cancer cells via regulation of PPP1R15A, TRIB3, and ATF3 gene expression." (PMID 35283426, 2022). "In addition, the greater increase in TRIB3 expression via gossypol treatment in BxPC-3 cells than that in MIA PaCa-2 cells may not only correlate with higher toxicity, but could also result in a better therapeutic effect against pancreatic cancer cells containing wild-type KRAS." (PMID 35283426, 2022).
Parkinson disease (2 papers, 2017 to 2019). A progressive degenerative disorder of the central nervous system characterized by loss of dopamine producing neurons in the substantia nigra and the presence of Lewy bodies in the substantia nigra and locus coeruleus. "TRIB3 is elevated and mediates cell death in Parkinson’s disease." (PMID 31191318, 2019). "Interestingly, a TRIB3-regulated AKT-FOXO transcriptional network also operates in human neurons, where TRIB3 expression levels are inversely correlated with the Parkinson's disease-associated ubiquitin E3 ligase PARKIN." (PMID 27908682, 2017). "Indeed, TRIB3, but not TRIB1 or TRIB2, mRNA expression is upregulated in the developing murine brain and TRIB3 immunostaining is markedly increased in sections of substantia nigra from Parkinson's disease brains." (PMID 27908682, 2017). "TRIB3 induction also occurs in response to neurotrophic factor (NGF) deprivation, Parkinson’s disease, and metabolic stress." (PMID 31191318, 2019).